CALM3 (calmodulin 3)
Description:
Calmodulin acts as part of a calcium signal transduction pathway by mediating the control of a large number of enzymes, ion channels, aquaporins and other proteins through calcium-binding. Calcium-binding is required for the activation of calmodulin. Among the enzymes to be stimulated by the calmodulin-calcium complex are a number of protein kinases, such as myosin light-chain kinases and calmodulin-dependent protein kinase type II (CaMK2), and phosphatases. Together with CCP110 and centrin, is involved in a genetic pathway that regulates the centrosome cycle and progression through cytokinesis. (Microbial infection) Required for C.violaceum CopC and S.flexneri OspC3 arginine ADP-riboxanase activity.
Synonyms: CAMIII; PHKD; PHKD3; CALM; CAM1; CAM2; CAMB; CPVT6; CaM; HEL-S-72; LQT16
Tractability: Small molecule: a structure with a bound ligand is known; it belongs to a druggable protein family. Antibody: its Gene Ontology location is reachable by antibodies, with high confidence. PROTAC: UniProt records ubiquitination sites on it.
Gene: Protein-coding gene on chromosome 19 (46,601,074 to 46,610,787, forward strand). Ensembl gene ENSG00000160014.
Subcellular location: Cytoplasm, cytoskeleton, spindle; Cytoplasm, cytoskeleton, spindle pole; Cytoplasm, cytoskeleton, microtubule organizing center, centrosome
Pathways (Reactome):
Disease: Enterobacterial factors antagonize host defense
Immune System: CASP4 inflammasome assembly
Gene Ontology:
Molecular function: adenylate cyclase activator activity; adenylate cyclase binding; calcium channel regulator activity; calcium ion binding; protein binding; protein kinase binding; protein phosphatase activator activity; protein serine/threonine kinase activator activity; titin binding; transmembrane transporter binding; calcium-dependent protein binding; nitric-oxide synthase binding; nitric-oxide synthase regulator activity; phosphatidylinositol 3-kinase binding; protein domain specific binding; transporter inhibitor activity; type 3 metabotropic glutamate receptor binding
Biological process: calcineurin-mediated signaling; detection of calcium ion; negative regulation of high voltage-gated calcium channel activity; regulation of cardiac muscle cell action potential; regulation of cardiac muscle contraction; regulation of cardiac muscle contraction by regulation of the release of sequestered calcium ion; regulation of cell communication by electrical coupling involved in cardiac conduction; regulation of cytokinesis; regulation of heart rate; regulation of release of sequestered calcium ion into cytosol by sarcoplasmic reticulum; response to calcium ion; substantia nigra development; G protein-coupled receptor signaling pathway; long-term synaptic potentiation; negative regulation of calcium ion export across plasma membrane; presynaptic endocytosis; regulation of synaptic vesicle endocytosis; regulation of synaptic vesicle exocytosis; response to amphetamine; response to corticosterone
Cellular component: calcium channel complex; catalytic complex; centrosome; nucleus; protein-containing complex; sarcomere; spindle microtubule; spindle pole; vesicle; cytoplasm; cytosol; myelin sheath; plasma membrane; calyx of Held; chromatin; growth cone; membrane; mitochondrial membrane; postsynaptic cytosol; presynaptic cytosol; Schaffer collateral - CA1 synapse; sperm midpiece; spindle; synaptic vesicle membrane; voltage-gated potassium channel complex
Genetic constraint (gnomAD): Loss-of-function variants: 5 observed, 18.9 expected, observed/expected ratio (o/e) 0.26, 90% interval 0.14 to 0.56. The upper end of that interval is the gene's LOEUF score, 0.56, which puts it in group 2 of 6, group 1 being the genes least tolerant of losing a copy. Missense variants: 57 observed, 196.43 expected, observed/expected ratio (o/e) 0.29, 90% interval 0.23 to 0.36. Synonymous variants: 69 observed, 70.58 expected, observed/expected ratio (o/e) 0.98, 90% interval 0.8 to 1.2.
Gene-disease validity (ClinGen):
ClinGen rates the evidence that CALM3 causes each of these diseases.
long QT syndrome (autosomal dominant): Definitive.
catecholaminergic polymorphic ventricular tachycardia (autosomal dominant): Moderate. Catecholaminergic polymorphic ventricular tachycardia (CPVT) is a severe genetic arrhythmogenic disorder characterized by adrenergically induced ventricular tachycardia (VT) manifesting as syncope and sudden death.
Homologues: Orthologues: chimpanzee CALM3 (100% identical), dog CALM3 (100% identical), guinea pig CALM3 (100% identical), mouse Calm3 (100% identical), rat Calm3 (100% identical), zebrafish calm1a (100% identical), zebrafish calm1b (100% identical), pig CALM3 (94% identical), macaque CALM3 (89% identical), Caenorhabditis elegans cal-1 (66% identical), Caenorhabditis elegans cal-3 (58% identical), Caenorhabditis elegans tnc-2 (45% identical), and 5 more. Paralogues in human: CALM1 (100% identical), CALM2 (100% identical), CALML3 (85% identical), CETN1 (53% identical), CETN2 (51% identical), CALML5 (50% identical), CALML6 (46% identical), CABP2 (45% identical), CABP4 (44% identical), CABP5 (44% identical), CALML4 (44% identical), CABP1 (43% identical), and 8 more.
Diseases named in the same sentence as CALM3 in open-access papers:
CALM3 is named in the same sentence as 39 diseases in open-access papers, as found by Europe PMC text mining. Sharing a sentence is not in itself a finding about the gene and the disease. The quoted sentences say what the papers report.
catecholaminergic polymorphic ventricular tachycardia (6 papers, 2017 to 2025). "The hereditary pro-arrhythmic condition catecholaminergic polymorphic ventricular tachycardia (CPVT), is associated with gene mutations involving ryanodine receptor type 2 (RYR2), calsequestrin (CASQ2), triadin (TRDN) or calmodulin (CALM1, CALM2 and CALM3)." (PMID 34643236, 2021).
breast cancer (5 papers, 2015 to 2022). A primary or metastatic malignant neoplasm involving the breast. "Calmodulin-like proteins, namely CALM2 and CALM3, were also upregulated in saliva of bitches with mammary tumors." (PMID 32344524, 2020). "A decrease in CALM1 has been reported for CD4+ TIL in breast cancer, and CALM3 expression in TIL has been shown to be higher in extensively infiltrated tumors vs minimally infiltrated tumors suggesting a possible association between CaM levels and tumor infiltrating abilities of T cells." (PMID 32184726, 2020). "Of note, only the MDA-MB-231 breast cancer cell line showed a dependency on KRAS, CALM3 as well as PPP2CA." (PMID 35617282, 2022). "Analysis of differential expression levels highlighted CLDND1, PLEKHA2, ACSL3, SLC30A9, MSN, CALM3 and PRKAR1A as potential regulators of breast cancer cell survival since they were affected by PKCδ siRNA in all cell lines." (PMID 26083392, 2015).
long QT syndrome (5 papers, 2017 to 2025). "CALM3 variants are associated with long QT syndrome and ventricular arrhythmias, and more recently idiopathic ventricular fibrillation and cardiomyopathy, and have been described in young sudden death cases." (PMID 38229148, 2024). "Previous researches have showed that mutation of CALM2 or CALM3 was the main reason for catecholamine-sensitive ventricular tachycardia and long QT syndrome." (PMID 33330659, 2020). "Meanwhile, CALM3 gene was involved in the progression of several diseases, such as cardiomyopathy, ventricular tachycardia, and long QT syndrome." (PMID 38361757, 2024).
Alzheimer disease (4 papers, 2017 to 2025). A progressive, neurodegenerative disease characterized by loss of function and death of nerve cells in several areas of the brain leading to loss of cognitive function such as memory and language. "Among these M2 genes on Chromosome 19, CALM3 encoding calmodulin has garnered attention in Alzheimer’s disease (AD) research; APOE4 and APOC1A has been acknowledged as risk factors for late-onset AD." (PMID 41459526, 2025). "In the Alzheimer’s disease pathway, we found genes up-regulated (Apbb1, Atf6, Cacna1d, Calm3, Casp7, Itpr1, Lpl, and Ppp3ca) and down-regulated (Aph1b, Bid, Cycs, Fadd, Fas, and Nae1)." (PMID 28513549, 2017). "In CN samples, interestingly, among the most significant pathways enriched with significant CpGs is the KEGG pathway “Alzheimer’s disease”, which was curated based on recent AD literature and included genes that confer AD risks, such as APOE, PSENEN, MAPT, CALM3, MME, and others." (PMID 37038196, 2023).
cardiac arrhythmia (4 papers, 2017 to 2024). Any disturbances of the normal rhythmic beating of the heart or MYOCARDIAL CONTRACTION. "Downregulation of CALM1 is predicted to cause electrical dysfunctions in muscle and is associated with cardiac arrhythmias; however, redundancy exists in the form of CALM2 and CALM3, which may mitigate this effect." (PMID 38793603, 2024). "Thus far the technology is being explored for possible treatment of monogenic disorders, including cardiac arrhythmias caused by mutations in the CALM1, CALM2 or CALM3 genes." (PMID 35459248, 2022).
diabetes (2 papers, 2022 to 2023). "Furthermore, the two signaling nodes in the inter-organ mechanism of IPF proposed in our study, CALM1/CALM2/CALM3 (in the lung) and PCK1 (in the liver), are both molecularly linked to diabetes." (PMID 38081956, 2023).
Parkinson disease (2 papers, 2009 to 2022). A progressive degenerative disorder of the central nervous system characterized by loss of dopamine producing neurons in the substantia nigra and the presence of Lewy bodies in the substantia nigra and locus coeruleus. "These include genes in the pathways for amyotrophic lateral sclerosis (NEF3, NEFL, NEFH), Huntington's disease (CALM3, CLTC, CLTB), neurodegenerative disorders (APLP1, NEFH, FBXW7), Parkinson's disease (GPR37) and prion disease (APLP1, NFE2L2)." (PMID 19948073, 2009). "From the Parkinson’s disease KEGG enrichment result, five of differently expressed piRNAs-aligned genes (NDUFA4, CALM3, UCHL1, CALM2, and HSPA5) in the prefrontal cortex (15 genes) overlapped with differently expressed piRNAs-aligned genes in the amygdala (16 genes)." (PMID 35269612, 2022).
atherosclerosis (1 paper, 2022). A disease characterized by the build-up of fatty material and calcium deposition in the arterial wall resulting in partial or complete occlusion of the arterial lumen. "Similar to APOB and CD36, the CALM1, CALM2, and CALM3 encoding calmodulin 1, 2, and 3, respectively were differentially expressed and downregulated on the lipid and atherosclerosis pathway." (PMID 36506940, 2022). "The genes that were differentially expressed in the lipid and atherosclerosis pathway were APOB (P = 0.008), CD36 (P = 0.040), CALM1, CALM2, CALM3 (P = 0.015), and HSPA8 (P = 0.047)." (PMID 36506940, 2022).
cocaine addiction (1 paper, 2025). "CALM3 and JUN were downregulated in the cocaine addiction group compared to controls (p < 0.05), whereas CCL2, CD44, CLIC1, and VCAM1 were upregulated (p < 0.05)." (PMID 41465087, 2025).
colitis (1 paper, 2015). Inflammation of the colon. "CALM3 and PKCζ gene expression in the colitis with SD group increased significantly compared with the colitis group, and their expression levels decreased in the melatonin-treated group." (PMID 25625560, 2015).
endometrial cancer (1 paper, 2023). Primary or metastatic malignant neoplasm involving the endometrium (mucous membrane that lines the endometrial cavity). "The four-marker panel comprising SPR1B, TXN, CRNN and CALM3 predicted endometrial cancer with an AUC of 0.78 (0.69–0.88)." (PMID 36807337, 2023).
glioma (1 paper, 2021). A benign or malignant brain and spinal cord tumor that arises from glial cells (astrocytes, oligodendrocytes, ependymal cells). "However, in the CGGA dataset, only CALD1, CALML4 and CALML6 were associated with IDH wildtype glioma, and no specific relationship with CALM3, CALM1 and CALM2 expression was noticed." (PMID 34070840, 2021). "The expressions of CALML5, CALM3 and CALML3 were upregulated in IDH mutant glioma." (PMID 34070840, 2021).
Hypertension (1 paper, 2024). The presence of chronic increased pressure in the systemic arterial system. "Three machine learning algorithms identified five biomarkers associated with hypertension: calmodulin 3 (CALM3), cluster of differentiation 9 (CD9), growth factor independence 1B transcriptional repressor (GFI1B), myosin light chain kinase (MYLK), and Ras suppressor-1 (RSU1)." (PMID 39519602, 2024). "The intersection of the three machine learning algorithms identified five genes as potential key biomarkers for hypertension: calmodulin 3 (CLAM3), CD9, growth factor independent 1B transcriptional repressor (GFI1B), myosin light chain kinase (MYLK), and Ras Suppressor Protein 1 (RSU1)." (PMID 39519602, 2024). "However, we found that CALM3 and CD9 did not exhibit significant expression differences between the hypertension and control groups, and ROC analysis indicated low reliability for these genes as hypertensive biomarkers." (PMID 39519602, 2024).
laryngeal carcinoma (1 paper, 2018). Carcinoma that arises from the laryngeal epithelium. "Among 275 investigated proteins, 12 crucial proteinsare determined that 4 of them can be introduce as a possible biomarker panel includingYWHAZ, PPP2R1A, HSP90AA1, and CALM3 for human laryngeal cancer." (PMID 29755572, 2018). "We choose cutoff 1200 for degree and therefore YWHAZ and PPP2R1A as the toptwo up-regulated genes and also HSP90AA1 and CALM3 as the top two down-regulated genes areintroduced as human laryngeal cancer." (PMID 29755572, 2018). "Finally, a possible biomarker panelincluding YWHAZ and PPP2R1A as the two up-regulated genes and HSP90AA1 and CALM3 as the twodown-regulated genes for human laryngeal cancer is introduced." (PMID 29755572, 2018).
liver cancer (1 paper, 2024). An epithelial or non-epithelial malignant neoplasm that arises from the liver. "CALM3+CD8+ T cells-C1 cells are highly expressed in most metabolic signaling pathways, so glycogen metabolism may be one of the prognostic factors affecting patients with liver cancer." (PMID 38361757, 2024).
lung carcinoma (1 paper, 2015). "Our gene-based analysis highlighted 17 lung cancer susceptibility genes, of which the most significant was CALM3 encoding calmodulin, which also significantly associated with pancreatic cancer risk." (PMID 25683757, 2015). "We identified 17 genes that were significantly associated with lung cancer risk (P < 0.05), among which CALM3 showed the most significance (P = 0.0022)." (PMID 25683757, 2015). "Nevertheless, little is known about the functions and cellular mechanisms of CALM3 in lung cancer." (PMID 25683757, 2015). "For lung cancer, we found 3 SNPs across three inositol phosphate metabolism genes with P < 0.001, including rs13021302 (INPP5D), rs11083841 (CALM3), and rs11668501 (ITPKC)." (PMID 25683757, 2015).
Oral cancer (1 paper, 2020). "In the present study, the inhibitory role of the alpha mangostin on the genes implicated in Oral cancer namely CALM3, ARRB1, HTT, and FLNAwas investigated through molecular docking techniques." (PMID 33214751, 2020). "Background and Aim: The genes ARRB1, FLNA, CALM3, and HTT are commonly expressed in oral cancer and have been hypothesized to be involved in the carcinogenic pathway." (PMID 33214751, 2020).
ovarian carcinoma (1 paper, 2024). A malignant neoplasm originating from the surface ovarian epithelium. "Notably, expression levels of RPS6, RPL12, CTNNB1, RPL7, RPS2, and CALM3 did not have any impact on the survival of ovarian cancer patients." (PMID 39309198, 2024).
squamous cell carcinoma (1 paper, 2019). A carcinoma arising from squamous epithelial cells. "Overexpression of CFBF, PAGE2, CALM3, DSG3, CTAG2, and FAM83C was seen only in squamous cell carcinoma." (PMID 31877723, 2019).
cancer (7 papers, 2009 to 2023). A tumor composed of atypical neoplastic, often pleomorphic cells that invade other tissues. "Similarly, CALM2 and CALM3 also had high prognostic and diagnostic potentials in human cancers." (PMID 35096010, 2021). "Using the Cancer Cell Line Encyclopedia (CCLE), we assessed the correlation between the expression of the three genes encoding human CaM (CALM1, CALM2 and CALM3) and the IC50 values for CWHM-974 and FLU in the cancer cell lines tested." (PMID 37909019, 2023). "The Calmodulin 3 (CALM3) is considered the major regulator of Ca2+ dependent signaling in all eukaryotes which assists in tumor growth, tumor-associated angiogenesis, metastasis and involved in various pathways associated with survival of the cancer cells." (PMID 28559546, 2017). "In conclusion, we detected significant under-expression of genes SLC26A3, TPM1, DCN and CALM3 in CRC, providing further evidence of their decreased mRNA expression and thus implicating them in the development of this type of cancer." (PMID 19678923, 2009). "CALM1/CALM2/CALM3, the latent IPF-features are the known downstream targets of KNG1 (ligand)—BDKRB1 (receptor) signaling (KEGG: hsa05200, Pathways in cancer)." (PMID 38081956, 2023).
tumor (6 papers, 2017 to 2024). "Cell types that are highly expressed in tumor tissues compared to normal tissues are CALM3+CD8+T cells-C1 and UGP2+Mac-C2 (p < 0.05)." (PMID 38361757, 2024). "Calmodulin which is encoded by CALM1, CALM2, and CALM3 genes, plays a significant role in non-tumor cell migration as well as tumor migration and metastasis." (PMID 36506940, 2022). "Therefore, it may be inferred that CALM3 inhibits tumor immunity by inhibiting CD8+T cells through glucose metabolism, thus leading to poor prognosis of HCC with high expression of CALM3+CD8+ T cells-C1 cell clusters." (PMID 38361757, 2024). "The expression of ARRB1, FLNA, CALM3 and HTT was found to be localized predominantly in the cytoplasm of the tumor cells." (PMID 28559546, 2017).
cardiovascular disease (1 paper, 2025). "Together, the reduction in OXCT1 and CALM3 observed in protein-restricted fetuses highlights an early metabolic and structural vulnerability that may predispose the heart to maladaptive remodeling and cardiovascular disease in later life." (PMID 41244074, 2025).
neurodegenerative disease (1 paper, 2015). A disorder of the central nervous system characterized by gradual and progressive loss of neural tissue and neurologic function. "The prevalent pathways that were differentially affected during male ageing relate to neurodegenerative diseases such as HD, AD, and PD; in this case, the implicated genes (CASP7, CALM3, CYCS, SDHC, multiple subunits of Complex I, Complex IV, and ATP synthase) are downregulated." (PMID 25977747, 2015).
CALM3 also shares sentences with these, for which no sentence is quoted: cardiomyopathy (2 papers); familial hypertrophic cardiomyopathy (2); idiopathic ventricular fibrillation (2); Ventricular arrhythmia (2); ventricular tachycardia (2); alcoholism (1); amyotrophic lateral sclerosis (1); Arrhythmia (1); beta thalassaemia (1); cardiac arrest (1); epilepsy (1); HIV-1 infection (1); Huntington disease (1); neuropathy (1); pancreatic cancer (1); prion disease (1).